FXR1 (FMR1 autosomal homolog 1)
Diseases named in the same sentence as FXR1 in open-access papers (continued):
Sharing a sentence is not in itself a finding about the gene and the disease.
cancer (continued). "FXR1 expression correlates with disease-specific survival (DSS), and overall survival (OS) in several cancer pathways, further in progression-free interval (PFI) in most cancers." (PMID 38050239, 2023). "Although recent work that examined FXR1 in human cancers showed silencing of FXR1 exhibited reduced cancer cell growth in vitro and in vivo, the precise molecular mechanism of FXR1-regulated cancer cell growth was not addressed." (PMID 27606879, 2016). "As expected the level of FXR1 is highly amplified in cancer tissues compared to normal adjacent tissues and we do not see differential expression of FMR1 and FXR2." (PMID 27606879, 2016). "Thus, FXR1 is an important protein that regulates RNAs such as p21 and TERC to promote cancer progression." (PMID 27606879, 2016). "Our RNA-seq and eCLIP analysis showed that silencing FXR1 can have both cancer positive and negative effects on gene expression, suggesting that the recognition of G4-region may influence mRNA turnover regulation." (PMID 38709899, 2024). "Therefore, a more thorough investigation is needed to ascertain the specific role of the FXR1 and establish customized approaches for targeted FXR1 cancer therapy strategies without damaging nearby healthy cells." (PMID 38238286, 2024). "However, how FXR1 recognizes tumor suppressor genes and block their expression in cancer cells has never been established." (PMID 31940341, 2020).
tumor (37 papers, 2014 to 2026). "Then we found it targets tumor through the FXR1-IL-35 axis and causes CD4+ T cells into IL-35-producing induced regulatory T cells (iTr35) to activate anti-tumor immunity to enhance the anti-tumor ability." (PMID 40259042, 2025). "As previously stated, FXR1 has been associated with tumor development and resistance to anticancer drugs." (PMID 38238286, 2024). "Multivariable Cox analysis further indicates that FXR1 protein expression was associated with DMFS after adjusting for tumor stage in TNBC (P = 0.03, HR, 6.37, 95% CI, 1.2–33.7)." (PMID 28387221, 2017). "FBXO4 knockdown predominantly rescued the tumor-suppressive phenotype in FXR1-deficient cells." (PMID 36498797, 2022). "Single-cell RNA sequencing (scRNA-seq) analysis of ascites composed of tumor, stromal, and immune cells analysis reveals that FXR1 silencing suppresses tumor cell proliferation and reduces tumor-promoting M2-like macrophages." (PMID 41932914, 2026). "FXR1 silencing also increases cytotoxic T cells, NK cells, and dendritic cells with anti-tumor characteristics in vivo." (PMID 41932914, 2026). "This suggests to us that cDHPs most likely inhibit the FXR1-IL-35-ACTR3 axis to block tumor proliferation, immune evasion, and metastasis." (PMID 40259042, 2025). "Through regulating CDC6, FXR1 overexpression boosted tumor growth and oxaliplatin resistance in colorectal cells, while knockdown improved their sensitivity." (PMID 38238286, 2024). "More importantly, as our model illustrates, we showed that PRMT5-activated FXR1 is intricate in controlling the mRNA expression of its targets, playing both tumor-activating and tumor-suppressive roles." (PMID 38709899, 2024). "In this study, we investigated the expression difference of FXR1 in different tumors, its influence on tumor microenvironment and tumor prognosis, and the influence of FXR1 gene expression on tumor proliferation." (PMID 38050239, 2023). "Exosomal circZNF451 reshapes the tumor immune microenvironment by inducing macrophages polarization via the FXR1- ELF4–IRF4 axis and is a novel biomarker for predicting the sensitivity of PD1 blockade in LUAD." (PMID 36209117, 2022). "This creates a consistent picture of SCFFbxo4 as critical regulator of tumor development affecting uncontrolled proliferation, senescence bypass (D1, Fxr1) and tumor progression (hnRNPK)." (PMID 36329064, 2022). "High expression of FXR1 in UCB patients was positively associated with advanced T and N stage, tumor grade, and tumor volume (p < 0.05)." (PMID 35194031, 2022). "FXR1 has been investigated in oncology for its potential role as a key regulator of tumor progression." (PMID 36498797, 2022). "Another study showed that the overexpression of FXR1 facilitates the bypass of senescence and tumor progression." (PMID 35886008, 2022). "We further showed that the effects of enhanced colony formation, cell proliferation, and subcutaneous xenograft tumor growth induced by overexpression of FXR1 were largely inhibited upon TRAF1 silencing in vivo and in vitro." (PMID 35194031, 2022). "The results showed that FXR1 knockdown via short hairpin RNA (shRNA) lentiviral infection resulted in markedly decreased tumor organoid growth." (PMID 35194031, 2022). "Overall, the results of this study indicate that LTA4H and FXR1 are extensively expressed in canine oral melanomas and suggest that they can play a role in tumor oncogenesis process." (PMID 34966807, 2021). "Remarkably, FXR1 knockdown combined with inhibition of MIR17HG resulted in the smallest tumor volumes and the longest survivals of nude mice in vivo." (PMID 30691465, 2019). "In contrast to sh-FXR1-NC + sh-MIR17HG-NC group, sh-FXR1 + sh-MIR17HG-NC, sh-FXR1-NC + sh-MIR17HG and sh-FXR1 + sh-MIR17HG groups led to smaller tumor volumes." (PMID 30691465, 2019).
tumor (continued). "Fxr1 can also form a complex with PRKCI and ECT2, which controls cell proliferation/cell survival and links Fxr1 expression with human tumours; of note, elevated Fxr1 mRNA levels correlate with poor prognosis." (PMID 29142209, 2017). "Western analysis of lysates from frozen HNSCC tumour and adjacent normal tissues revealed Fxr1 elevation in tumour tissues; notably, Fbxo4 levels were reduced relative to normal in four out of six tumours with elevated Fxr1." (PMID 29142209, 2017). "In this manner, the modest increase of Fxr1 expression will have a profound impact on tumorigenesis by virtue of its capacity to suppress a documented tumour suppressor, Fbxo4, resulting in overexpression of pro-neoplastic SCFFbxo4 targets." (PMID 29142209, 2017). "Among those shown significant alteration, FXR1 showed a 31% alteration in a combined DNA copy number and mRNA in 279 tumor samples." (PMID 27606879, 2016). "FXR1 mRNA is overexpressed in tumor compared to normal adjacent tissues, whereas FMR1 and FXR2 mRNA levels are comparable to their normal mRNA expression." (PMID 27606879, 2016). "Next, we tested the mRNA levels of FXR1 in eight matched tumor vs normal adjacent samples (obtained from HNSCC patients from MUSC biorepository) by qRT-PCR (clinical parameters are tabulated in S5 Table)." (PMID 27606879, 2016). "Therefore, FXR1 silencing in tumor tissues provides an effective strategy to treat tumors expressing high levels of FXR1." (PMID 41932914, 2026). "In this study, we found that cDHPs inhibited the growth of lung adenocarcinoma (LUAD) transplants in mice and prevented the conversion of CD4+ T cells into IL-35-producing induced regulatory T cells (iTr35) to activate anti-tumor immunity by inhibiting the FXR1-IL-35 axis." (PMID 40259042, 2025). "However, elucidated the crucial role by the FXR1-IL-35-ACTR3 axis in mediating the anti-tumor and immune regulatory effects." (PMID 40259042, 2025). "FXR1 shows high methylation levels and can have more preference to bind G4-RNAs containing regulatory signals for generating proteins that are crucial for encouraging tumor growth." (PMID 38709899, 2024). "FXR1 deletion in mice reduced tumor development by down-regulating oncogenic gene expression." (PMID 38238286, 2024). "FXR1 has been related to almost every step leading to tumor formation." (PMID 38238286, 2024). "Furthermore, we analyzed FXR1 mRNA expression in 23 different tumor types with paired samples from TCGA." (PMID 38050239, 2023). "As a result of these findings, we hypothesize that immune cells affect tumor survival in a manner that is correlated with the level of FXR1 expression." (PMID 38050239, 2023). "The findings indicated significant variations in FXR1 expression, across most tumor types." (PMID 38050239, 2023). "Here, we show that in LUAD, tumor-derived exosomal circZNF451 may elicit ubiquitination of FXR1 via the E3 ligase TRIM56 in macrophages." (PMID 36209117, 2022). "In the Balb/c nude mouse model, we further proved that the enhancement of subcutaneous xenograft tumor growth induced overexpression of FXR1 could be restored by TRAF1." (PMID 35194031, 2022). "All these data indicate that FXR1 may act as a promoter of tumor progression and metastasis, including in UM." (PMID 36498797, 2022). "Although LTA4H and FXR1 seem unrelated to tumor behavior, their extensive expression in the present cohort of cases suggest that they may play a role in canine oral melanoma oncogenesis." (PMID 34966807, 2021). "RNA pull-down and RNA immunoprecipitation assays demonstrated that ENST00000508435 could directly bind to FXR1 to promote tumor metastasis." (PMID 34057025, 2021).
tumor (continued). "Additionally, Qihong Huang identified a novel ribonucleprotein (RNP) complex (hnRNPK, FXR1, FXR2, PUF60, SF3B3), which is required for translational regulation of lncRNA to cause tumor invasion and metastasis." (PMID 34057025, 2021). "Conversely, overexpression of Fxr1 facilitates the bypass of senescence and tumour progression." (PMID 29142209, 2017). "Regulation of ECT mRNA stability via FXR1 may also contribute to FXR1 oncogenic effects, while the tumour suppressor effects of miR-223 may be partly mediated by targeting the ECT2 3’UTR." (PMID 28806777, 2017). "FXR1 is highly expressed in tumor compared to normal adjacent tissues." (PMID 27606879, 2016). "Besides, FXR1 inhibition combined with MIR17HG inhibition produced the smallest tumor volume." (PMID 30691465, 2019). "Fxr1 may have more roles in tumours and it is a reasonable target for investigation." (PMID 29142209, 2017). "In summary, we suggest that Dendrobium houshanense are likely to directly regulate NSCLC proliferation through FXR1, regulate the tumor microenvironment through FXR1-IL-35-ACTR3 axis, and influence tumor cell migration and invasion." (PMID 40259042, 2025). "Moreover, our enrichment analysis indicates that FXR1 could influence tumor etiology or pathogenesis via multiple pathways, encompassing cell cycle regulation, the electron transport chain oxphos system in mitochondria, complement and coagulation cascades, and the cornified envelope formation." (PMID 38050239, 2023). "Survival analysis disclosed a correlation between FXR1 expression and OS, PFI, and DSS in multiple tumor types." (PMID 38050239, 2023). "FXR1, FXR2 and hnRNPK are required for these treRNA functions, while their expression promotes tumour invasion in vitro and metastasis in vivo." (PMID 34044876, 2021). "Remarkably, inhibition of FXR1 and MIR17HG in combination largely reduced xenograft tumor growth and prolonged the nude mice survival." (PMID 30691465, 2019). "More importantly, knockdown of FXR1 and MIR17HG in combination significantly reduced xenografts tumor growth." (PMID 30691465, 2019). "FXR1 mRNA levels along with two other FXR1 families of proteins FMR1 and FXR2 were determined in 521 tumor samples." (PMID 27606879, 2016). "Collectively, our data show that FXR1 DNA, mRNA, and protein is amplified and expressed at high levels in HNSCC tumor tissues and cell lines." (PMID 27606879, 2016). "After release from PGRMC1, FXR1 and RBM39 bind and stabilize progesterone receptor (PR) transcript to enable expression of PR protein, which induces cell cycle, membrane, and cytoskeleton remodeling genes that drive tumor growth." (PMID 42282014, 2026). "We further investigated the effect of high expression of IL-35-related FXR1 and ACTR3 on tumor microenvironment (TME) and found that ACTR3 was significantly associated with EMT signatures and FXR1 was positively associated with NSCLC signatures, which were significantly and positively correlated." (PMID 40259042, 2025). "It remains to be determined whether the FXR1/TRAF1 axis, shown here, is indeed essential to promote tumor formation." (PMID 35194031, 2022). "FXR1 and FMR1 mRNAs are significantly (p<0.0001) expressed in tumor samples compared to normal." (PMID 27606879, 2016). "In order to investigate FXR1 and TRAF1 expression in paired UCB tissues from SYSUCC, we collected another eight paired UCB and paracancerous tissues and found the protein levels of both FXR1 and TRAF1 were frequently upregulated in tumor tissue compared with paracancerous tissue." (PMID 35194031, 2022). "That is, FXR1 mediated tumour growth not cell proliferation." (PMID 34044876, 2021).
tumor (continued). "As can be seen from the results in the first group (both male and female) failed to grow any tumor in FXR1 knockdown side compared to the control side, whereas in the second batch, the male mice had the nodule on the shFXR1 injected flank which did not grow up to the control flank." (PMID 31940341, 2020). "In addition, PKP3 could closely bind to RNA-binding proteins such as FXR1 and PABPC1, indicating that PKP1/2/3 can participate in cell connection and tumor progression through its interacting proteins." (PMID 33088217, 2020). "Moreover, knockdown of hnRNPK or FXR1 but not FXR2 increased the tumour growth of mouse model with MCF7 cells, whereas double knockdown or triple knockdown of the RNA-binding proteins significantly decreased primary tumour growth." (PMID 34044876, 2021).
infection (6 papers, 2018 to 2026). The state of being infected such as from the introduction of a foreign agent such as serum, vaccine, antigenic substance or organism. "Since UBAP2L plays an important role in nucleating stress granules, we speculated that NSP3 affected the ability of FXR1 to associate with these structures through competition during infection." (PMID 38177924, 2024). "Recently, we identified that the hypervariable region (HVR) of SARS-CoV-2 NSP3 binds to FXR1 and disrupts stress granule formation during the early stages of infection." (PMID 41532757, 2026). "To establish if FMRP incorporation into stress granules is affected during infection, we investigated FXR1 localization during infection in VeroE6 cells." (PMID 38177924, 2024). "As the levels of N increased reflecting later stages of infection, FXR1 localization shifted and was evenly distributed throughout the cytoplasm similar to uninfected cells (Fig. EV5A,B)." (PMID 38177924, 2024). "We noted that the total levels of FXR1 increased during infection consistent with a previous study (Fig. EV5C)." (PMID 38177924, 2024). "The Protein:Protein interaction of FXR1 mapped specifically to the VEEV nsP3 Hypervariable Domain (HVD) within nsP3, and FXR1 moves from the nucleus to the viral replicase complexes during infection." (PMID 36680204, 2023). "In contrast, during MNV infection, only 5 out of 21 of the cross-core stress granules proteins displayed a high enrichment with G3BP1, namely ZC3HAV1, FXR1 and G3BP2." (PMID 31905230, 2020).
myopathy (4 papers, 2013 to 2024). A disease of the muscle in which the muscle fibers do not function properly. "Knockdown mutations of FXR1 in mice reduce limb musculature and result in early mortality and recessive mutations in humans results in multi-minicore myopathy." (PMID 37549140, 2023). "We report that recessive mutations in this particular exon of FXR1 cause congenital multi-minicore myopathy in humans and mice." (PMID 30770808, 2019). "Here, the authors show that mutations in FXR1 exon 15, which is alternatively spliced in muscle, cause multi-minicore myopathy in humans and in mouse models." (PMID 30770808, 2019). "Herein, we show that recessive mutations in exon-15 of FXR1 are associated with a novel multi-minicore myopathy in humans and mice that varies in severity depending on the consequences of each mutation." (PMID 30770808, 2019).
psychiatric disorder (3 papers, 2018 to 2025). A disorder characterized by behavioral and/or psychological abnormalities, often accompanied by physical symptoms. "The RNA-binding protein FXR1, a member of the fragile X protein family, has been linked to mental illnesses and disabilities." (PMID 39753370, 2025). "Parvalbumin (PV) interneurons play critical roles in cortical processing and have been implicated in FXR1-linked mental illnesses." (PMID 39753370, 2025). "Extending our approach to different FXR1 deficits and different types of cells will expand our understanding of the regulatory functions of FXR1 and the connection with mental illness." (PMID 39753370, 2025). "FXR1 emerges as an important regulator of RNA metabolism in the brain, with strong implications in neurodevelopmental and psychiatric disorders." (PMID 40136424, 2025). "The links between FXR1 and psychiatric disorders provide a strong incentive to gain an understanding of its roles in neural function." (PMID 39753370, 2025). "Despite the potential links of both FXR1 and PV interneurons to psychiatric disorders, to our knowledge there has been only one prior study of the role of FXR1 specifically in PV interneurons." (PMID 39753370, 2025). "Although not altered in individuals with FXS, FXR1 has been implicated in neurodevelopmental and psychiatric disorders." (PMID 39753370, 2025).
head and neck tumors (1 paper, 2024). "Head and neck tumors have limited survival and poor outcomes due to the overexpression of FXR1 and PRMT5." (PMID 38709899, 2024).
muscular disorders (1 paper, 2013). "Interestingly, Fxr1 knockdown in C2C12 myoblasts significantly affected the functional categories ‘cell cycle’, ‘skeletal and muscular system development and function’ and ‘skeletal and muscular disorders’." (PMID 23555284, 2013).
FXR1 also shares sentences with these, for which no sentence is quoted: cervical cancer (2 papers); neurological disorders (2); oral squamous cell carcinoma (2); bile duct cancer (1); colitis (1); congenital myopathy (1); endometrial cancer (1); esophageal squamous cell carcinoma (1); Gorlin syndrome (1); gynecological benign tumor (1); kidney clear cell carcinoma (1); medulloblastoma (1); mood disorder (1); muscle disorders (1); neurodegenerative disease (1); ocular melanoma (1); rectal cancer (1); Respiratory insufficiency (1); spinal muscular atrophy (1); stomach cancer (1); testicular cancer (1); testicular embryonic carcinoma (1); triple-negative breast carcinoma (1); urothelial carcinoma (1); urothelial carcinoma of the bladder (1).